TERT (telomerase reverse transcriptase)
Diseases named in the same sentence as TERT in open-access papers (continued):
Sharing a sentence is not in itself a finding about the gene and the disease.
melanoma (continued). "TERT promoter mutations are associated with clinicopathological characteristics of melanoma like advanced tumor stage, increased tumor thickness, ulceration, and metastasis." (PMID 37504268, 2023). "Some telomere length maintenance genes (TERC, OBFC1) regulate both nevus count and melanoma risk, while the majority regulate melanoma risk only (such as TERT, DKK2, NAF1)." (PMID 36834954, 2023). "In total, 49 of 70 melanomas (70%) harbored a TERT promoter mutation, including 1,295,228 C>T (n = 18), 1,295,250 C>T (n = 25), 1,295,242-43 CC>TT (n = 5), and 1,295,161 A>C (n = 1)." (PMID 36011010, 2022). "Among them is telomerase reverse transcriptase (TERT), which is widely mutated in a majority of cancers and ∼10% of melanoma." (PMID 34983823, 2022). "Recently, a single nucleotide polymorphism rs2853669 variant (at position −245) has been involved in the regulation of TERT promoter mutations on melanoma survival and recurrence." (PMID 35903534, 2022). "Based on BRAF, NRAS and TERT promoter mutations, the custom melanoma panel displayed a limit of detection of ~0.2% mutant allele frequency and showed significant correlation with droplet digital PCR." (PMID 35494035, 2022). "Both melanomas showed mutations in the TERT promoter region, and one additionally harbored an NF1 mutation." (PMID 36077603, 2022). "TERT promoter revertant mutation inhibits melanoma cell growth both in vitro and in vivo and promotes apoptosis." (PMID 35053139, 2022). "The frequency of mutations in the TERT promoter exceeds the frequency of any known noncoding mutations in melanoma." (PMID 35903534, 2022). "TERT promoter mutations in malignant melanoma mainly occur on two hot spots on chromosome 5, namely, C228T mutation and C250T mutation, which correspond to −124C>T and −146C>T in the translation initiation site, respectively." (PMID 35903534, 2022). "To date, mutations in the GC-rich TERT promoter region, which is commonly mutated in melanoma, have been technically difficult to detect in ctDNA using next-generation sequencing (NGS) panels." (PMID 35494035, 2022). "Overall, TERT promoter revertant mutation not only inhibited the growth of melanoma in vitro, but also in vivo." (PMID 35053139, 2022). "In contrast to our previous NGS study using a Thermofisher custom melanoma ctDNA panel, the ArcherDX custom melanoma ctDNA panel detected TERT promoter mutations in ctDNA." (PMID 35494035, 2022). "The most remarkable advancement in improving our understanding of the genetic role of TERT in human cancer was the landmark finding of mutations in the promoter region of the TERT gene in melanoma using whole-genome sequencing." (PMID 35135543, 2022). "In this study, we developed a custom melanoma NGS panel for detection of ctDNA, which encompasses the top 15 gene mutations in melanoma including the TERT promoter." (PMID 35494035, 2022). "Our data confirm that anchored multiplex PCR provided a sensitive and specific melanoma liquid biopsy assay that detects common TERT promoter mutations." (PMID 35494035, 2022). "TERT promoter mutations were detected from 31 urinary bladder, 19 pancreato-biliary, 22 hepatic, 12 malignant melanoma, and 12 other tumor samples." (PMID 35135543, 2022). "The ability to detect somatic TERT promoter mutations co-occurring with BRAF or NRAS mutations is also valuable given that a TERT-mutation positive genetic profile is associated with a worse prognosis for melanoma patients." (PMID 35494035, 2022). "Since the first discovery of TERT promoter mutations in melanoma, an increasing number of studies have shown that TERT promoter mutations play an important role in tumorigenesis." (PMID 35739589, 2022). "Meanwhile, our studies not only validated that the TERT promoter revertant mutations inhibit melanoma growth both in vitro and in vivo, but also elucidated for the first time the relationship between TERT promoter revertant mutation and apoptosis." (PMID 35053139, 2022).
melanoma (continued). "Point mutations in the TERT promoter range are long known to cause telomerase activation and cell proliferation of all types of melanoma cells." (PMID 35053139, 2022). "Collectively, the results of our work demonstrate that reverting mutations in the TERT promoter is a potential therapeutic option for melanoma." (PMID 35053139, 2022). "The custom melanoma panel detected only 50% of these four cases (based on detection of a TERT C250T mutation and a MAP2K1 H119Y mutation respectively)." (PMID 35494035, 2022). "A total of seven TERT promoter mutations were identified in melanoma, −124C>T, −146C>T, −124/125CC>TT, −138/139CC>TT, −136C>T, −100C>T, and family variants −57A>C." (PMID 35903534, 2022). "We found no obvious association of this variation either with somatic TERT mutation or patient outcomes in our melanoma cohort." (PMID 35494035, 2022). "TERT promoter mutations are common mutations in melanoma and were first described in familial and sporadic melanoma." (PMID 35903534, 2022). "Based on a TERT mutation frequency of 15-60% in triple wild type melanoma the TERT mutation detection rate of 25% of our wild type melanoma patients using this panel falls within the frequency range." (PMID 35494035, 2022). "In primary melanoma with TERT promoter mutations, there is a tendency for the tumor thickness to increase." (PMID 35903534, 2022). "As MARK signalling plays an important role in melanoma, TERT mutations can lead to progression to invasive melanoma." (PMID 35837089, 2022). "The same group recently demonstrated the potential of probe-based ddPCR assays to specifically detect and quantify TERT promoter mutations in tumors and plasma of melanoma patients." (PMID 36579573, 2022). "TERT is a cancer-related gene, and mutations in the noncoding region of the TERT gene are considered to be the cause of most melanomas." (PMID 35903361, 2022). "Of these 103 cases, the TERT promoter mutations were detected in urinary bladder tumor (31/47, 66%), pancreato-biliary (19/127, 15%), hepatocellular carcinoma (22/41, 54%), and malignant melanoma (12/90, 13%)." (PMID 35135543, 2022). "All melanomas, except for one (sample #6), harbored at least one of the three cancer-associated TERT alterations: promoter point mutation, distal promoter methylation, or rearrangement." (PMID 36011010, 2022). "In the subgroup analysis of monotherapy and ICI combination therapy, only in the anticytotoxic T lymphocyte-associated antigen 4 (anti-CTLA4) group did patients with TERT mutations have a better prognosis, especially for melanoma." (PMID 35903534, 2022). "In previous reports, TERT promoter mutations have been linked to poor survival of melanoma patients." (PMID 35903534, 2022). "Although TERT promoter methylation was more prevalent in melanomas that contained wild-type TERT promoter, our data showed that methylation and mutation or rearrangement were not mutually exclusive at the sample level." (PMID 36011010, 2022). "Mutations in the telomerase reverse transcriptase (TERT) promoter melanomas are activatied in melanoma." (PMID 36614156, 2022). "TERT promoter mutations were first identified in sporadic and familiar melanomas, and subsequent investigations showed that they were present widely in many types of human malignancies." (PMID 36713366, 2022). "The melanoma additionally had mutations of TERT, DNMT3A, and PRSS3 and imbalanced chromosomal copy number gains in BRCA2, RET, FGFR1 (also referred to as FLT2), and IGF2." (PMID 35336833, 2022). "This highlights the need for any melanoma detection assay to include TERT promoter mutations in order to maximize detection rates in BRAF/NRAS WT patients." (PMID 35494035, 2022). "This peculiar distribution among BRAF functional classes in NSCLC is in contrast with data from melanoma and thyroid carcinoma patients, where TERT mutations have been mainly described in BRAF V600E-mutant tumors." (PMID 35884534, 2022).
melanoma (continued). "This review has described the research progress of TERT promoter mutations and telomerase in melanoma, the molecular mechanism of TERT promoter mutations, and the future treatment of melanoma patients with TERT promoter mutations." (PMID 35903534, 2022). "The discovery of hotspot mutations in the TERT core promoter, first in metastatic melanomas and subsequently in aggressive tumors of multiple lineages, revitalized the interest in understanding the mechanisms of telomerase reactivation in cancer." (PMID 35053525, 2022). "Mutations in the TERT promoter, first identified in melanoma, lead to increased transcription of the TERT gene." (PMID 35705560, 2022). "After 48 h, the cells hardly proliferated, suggesting that the TERT promoter revertant mutation can inhibit the growth of melanoma in vitro." (PMID 35053139, 2022). "This is a significant disadvantage because TERT promoter mutations are the most frequent recurrent mutations in melanoma, occurring in 34-80% of cutaneous melanomas and are associated with poor survival." (PMID 35494035, 2022). "In this experiment, after adjusting for age, location, histological subtype, Breslow thickness, ulcer, and tumor mitosis rate, TERT promoter mutations were still associated with fast-growing melanoma." (PMID 35903534, 2022). "As expected, the TERT promoter revertant mutation inhibited melanoma growth in vivo and in vitro through intrinsic apoptosis." (PMID 35053139, 2022). "The TERT promoter mutations were mainly detected in urinary bladder cancer (66%), hepatocellular carcinoma (54%), pancreato-biliary cancer (15%), and malignant melanoma (13%), and the overall incidence was similar to that reported previously." (PMID 35135543, 2022). "TERT promoter mutations that cause increased expression of telomerase (resulting in cell immortalization) are found in most low-CSD melanomas and have been identified as the second earliest alteration required for melanoma development." (PMID 34440462, 2021). "The frequency of TERT promoter mutation in melanoma varied widely among several reports, and the ratio of TERT C228T mutation was lower than that in other types of cancer." (PMID 34395278, 2021). "Novel recurrent somatic mutations in the core promoter region of TERT were recently identified in ~ 70% of melanoma samples examined by next-generation sequencing, which have now become the most frequently detected mutation in malignant melanoma." (PMID 33635430, 2021). "The relevance of telomere biology as a susceptibility pathway for familial melanoma is highlighted by the discovery of a germline mutation in the promoter of the TERT gene (c.-57T > G; rs878855297) co-segregating with melanoma in two unrelated families." (PMID 34356093, 2021). "In 2013, two cancer-specific hotspot somatic mutations in TERT promoter that activate TERT transcription were first identified in melanoma." (PMID 34395278, 2021). "Studies on the evolution of melanoma from precursor lesions have revealed that the vast majority of melanomas harbor TERT promoter mutations, indicating that these immortalizing mutations are selected at an unexpectedly early stage of neoplastic progression." (PMID 33427197, 2021). "There is a higher frequency of TERT promoter mutations in melanoma metastases and TERT amplification markedly increases in acral lentiginous melanoma metastasis." (PMID 35008286, 2021). "By investigating a melanoma-prone family by linkage analysis and high-throughput sequencing, disease-segregating germline mutations have been identified in the TERT gene, causing up to 2-fold increase in its transcription." (PMID 34123788, 2021).
melanoma (continued). "Mutations in telomerase reverse transcriptase (TERT), the gene encoding an enzyme crucial for telomere maintenance, also play a crucial role in melanoma development, with up to 50% of cutaneous melanomas harboring TERT promoter mutations." (PMID 34149718, 2021). "The melanoma-risk TERT rs2853676*A allele was also nominally associated with absence of mitoses, and the melanoma-risk rs401681*T allele was nominally associated with decreased log of Breslow thickness and absence of mitoses." (PMID 34898573, 2021). "Recurrent somatic mutations in melanoma and other cancers in the TERT promoter cause tumor-specific increase of TERT expression, resulting in the immortalization of the tumor cell." (PMID 33427197, 2021). "The melanoma-risk TERT rs2242652*T allele was positively associated with absence of mitoses, passing false discovery." (PMID 34898573, 2021). "The germline TERT-promoter mutation, despite its rarity, seems to be highly penetrant, since almost all carriers have developed early-onset melanoma and/or other tumor types." (PMID 34356093, 2021). "Previous studies reported an association between PAM with atypia and PAM-derived melanoma, with the presence of a TERT promoter mutation." (PMID 34071371, 2021). "The progression into the stage of RGP is often related to the acquisition of mutations (40–50% of melanomas) in the promoter of the TERT gene, that encodes for telomerase reverse transcriptase and drives melanoma cell immortality." (PMID 34830947, 2021). "TERT promoter mutations are frequently observed in malignant melanoma, bladder cancer, renal pelvis cancer, thyroid cancer, hepatocellular carcinoma, and malignant glioblastoma." (PMID 34477310, 2021). "The aims of this study were to standardize a highly sensitive methodology of digital PCR (dPCR) to accurately identify hotspot mutations in BRAF, NRAS, and TERT in plasma and interrogate its feasibility as a liquid biopsy tool for melanoma patients." (PMID 33122747, 2020). "The first studies that identified cancer related TERT promoter mutations were performed in melanoma patients." (PMID 32850962, 2020). "An example of such a mutation is the identification of mutations in the telomerase reverse transcriptase (TERT) promoter in melanoma and other cancers." (PMID 33024276, 2020). "cfDNA was analyzed for BRAF p.V600E, NRAS p.Q61K/p.Q61R, and TERT C228T mutations, as these are frequently found in melanoma patients." (PMID 32486146, 2020). "Recent data showed that TERT promoter mutations are commonly found in many cancers including melanomas, bladder cancers, and hepatocellular carcinomas." (PMID 32932803, 2020). "Ideally, detection of TERT promoter mutations needs to be included in any future workflow to maximize detection of melanoma based on ctDNA." (PMID 32785074, 2020). "TERT promoter mutations have been collectively associated with more aggressive melanomas and poorer outcomes, allowing to propose TERT promoter as a poor prognostic factor." (PMID 32784823, 2020). "This study aimed to elucidate the combined contribution of epigenetic (promoter methylation and chromatin accessibility) and genetic (promoter mutations) mechanisms in regulating TERT gene expression in healthy skin samples and in melanoma cell lines (n = 61)." (PMID 32267900, 2020). "The MAF of these TERT promoter mutations were low (in the range 0.15–0.8%) compared to values of 2–20% previously reported for a cohort of stage IV melanoma patients." (PMID 32785074, 2020).
melanoma (continued). "Our study has not only found a high frequency of TERT mutations in melanoma, but also a higher frequency of mutations in male melanoma patients." (PMID 32915164, 2020). "Mutations in the TERT promoter remain the most frequent mutations in the transcriptional regulatory regions in melanoma and other types of cancer." (PMID 33024276, 2020). "Other genes including CDKN2A, CDK4, BAP1, POT1, ACD, TERF2IP, and TERT are known for their high penetrance as predisposing mutations for melanoma." (PMID 33339193, 2020). "TERT promoter mutations are currently detected in ~40% of melanomas, with mutation frequencies varying between melanoma subtypes." (PMID 32784823, 2020). "Sanger sequencing on one naevus, fresh skin and cutaneous melanoma cell lines 518A2, 607B, A375, 94.07 and 93.08 revealed melanoma-associated TERT C250T and C228T mutations." (PMID 32267900, 2020). "Among melanomas, these rearrangements are mutually exclusive with the C228T and C250T mutations of the TERT promoter (P < 10−3)." (PMID 32025015, 2020). "Our study, although not ascertaining a predictive role of the TERTprom mutations, highlights the complexity of the pathways that underlie resistance to targeted therapy and regulate TERT expression and its impact on the prognosis in melanoma." (PMID 32290374, 2020). "A recent study on ddPCR assays for detecting TERT promoter mutations in melanoma has shown a similar LOD using TERT mutated melanoma cell lines." (PMID 33260905, 2020). "The results showed that patients with melanoma with TERT mutations (n = 43) had longer OS than those with wild type (n = 32) (P < .001)." (PMID 32810393, 2020). "In melanoma, a two-step mechanism was described, which showed that mutations in the TERT promoter region contribute to tumorigenesis." (PMID 32722302, 2020). "In particular, 73 out 115 SKCM melanoma samples (frequency of 63.4%) harbored TERT promoter mutations." (PMID 32850962, 2020). "Although point mutations cause TERT deregulation in UV-exposed melanomas, about 45% of ALMs have TERT copy number gains." (PMID 32825562, 2020). "A frequent TERT promoter polymorphism at −245 was associated with an increased rate of metastasis in melanoma and inversely correlated with BRAF mutation." (PMID 32850962, 2020). "Reported initially in melanoma, the TERT promoter mutations are frequent in multiple cancers, with some exceptions, arising from tissues with low rates of self-renewal." (PMID 32409749, 2020). "In summary, 19 out of 34 patients (55.9%) who had a TERT promoter mutation in the primary or metastatic lesion associated with a primary melanoma trunk site, developed visceral spreading as the first site of progression (OR 3.64, CI 1.14–11.66)." (PMID 30934988, 2019). "This SNP is located at a multi-cancer risk locus on chr5p15.33 and was found to have allele-specific regulatory activities on TERT expression, mutations of which have been associated with melanoma risk." (PMID 31203567, 2019). "Longer telomeres in melanoma families were associated to telomerase reactivation mainly due to TERT promoter mutations." (PMID 30884806, 2019). "Trunk melanomas have been associated in many studies to visceral involvement, TERT promoter mutation can be the biological explanation of trunk melanoma ability to skip regional metastases by promoting visceral spreading." (PMID 30934988, 2019). "Our findings encourage TERT mutation analysis at diagnosis in primary melanomas arising on the trunk since they are more likely progress to visceral site." (PMID 30934988, 2019). "Genetically, vertical growth and metastatic melanomas show a further increase in TERT mutational rate and, more generally, in the mutational load over radial growth melanomas." (PMID 30934534, 2019).